GSDME (gasdermin E)
Diseases named in the same sentence as GSDME in open-access papers (continued):
Sharing a sentence is not in itself a finding about the gene and the disease.
tumor (continued). "TMAO can induce gasdermin E (GSDME)-mediated tumor cell pyroptosis by activating the endoplasmic reticulum kinase PERK, leading to release inflammatory factors such as IL-1β and IL-18 into the tumor microenvironment." (PMID 40241220, 2025). "Our study is not the first to describe a tumor-promoting role of GSDME independent of its pyroptotic function in cancer." (PMID 40544161, 2025). "In tumor cells, PDT mediated by Ce6 stimulated ROS production and induced pyroptosis via GSDME." (PMID 40698137, 2025). "The tumor suppressor GSDME converts non-inflammatory apoptosis into inflammation-mediated pyroptosis through caspase cleavage." (PMID 40698137, 2025). "In addition to GSDME-mediated pyroptosis, the Cu-TBB nanomedicine releases Cu+ to generate ROS with O2 as a substrate in tumor cells, activating caspase-1-mediated classical pyroptosis via Gasdermin-D cleavage and promoting release of IL-1β, IL-18, and DAMPs." (PMID 40717985, 2025). "This indicates that GSDME is rather a tumor promoter than a suppressor in GB, independent of its pyroptotic function." (PMID 40544161, 2025). "Collectively, these findings indicate that DHN predominantly induced GSDME-dependent pyroptosis rather than apoptosis, ferroptosis, necroptosis, or cuproptosis in tumor cells." (PMID 40663398, 2025). "A pivotal study reported that caspase 3/GSDME-mediated pyroptosis is highly dependent on the basal level of GSDME and that tumor cells lacking ‘sufficient’ GSDME undergo apoptosis instead of pyroptosis in the context of chemotherapy." (PMID 40721578, 2025). "The authors observed CASP3 and GSDME cleavage of tumor cells in vivo but they did not profile the immune landscape to determine the impact on adaptive immunity and the establishment of antitumor immunity." (PMID 38391959, 2024). "There was hyperactivation of GSDMD, GSDME, and p-MLKL in dMMR tumor cells." (PMID 38740747, 2024). "To gain insight into the molecular mechanism of tumor cells, we performed RNA sequencing (RNA-seq) using tumor cells with or without overexpression of GSDME." (PMID 38853246, 2024). "The results in our mouse models showed that the combined group (OE + αPD1 group) had the smallest tumor volume and weight compared with other groups in both CT26 and MC38 animal models, which might suggest GSDME had synergistic effect with ICIs." (PMID 38853246, 2024). "They respond sequentially to the acidic tumor microenvironment and even more acidic intracellular conditions, such as in lysosomes, to ensure deep tumor penetration and targeted delivery of the chemotherapy drug doxorubicin (DOX) to the nucleus, where it provokes GSDME-mediated pyroptosis." (PMID 39221221, 2024). "Regarding the levels of caspase-3 no significant variation was observed following PTX administration neither in the case of normal cells neither tumor cells, suggesting the absence of caspase-3/GSDME signaling pathway." (PMID 39433537, 2024). "The T22-PE24 nanotoxin induced HCC pyroptosis via the caspase-3/GSDME signaling pathway and suppressed tumor growth in the absence of histological alterations in normal organs." (PMID 39559553, 2024). "Furthermore, by preventing the methylation of the DNA promoter in tumor cells, HYD-NDs can enhance the expression of GSDME." (PMID 38643134, 2024). "We further sought to confirm whether PA-induced cleavage of GSDME, including other gasdermin family proteins GSDMC and GSDMD, which have received much attention in tumor research." (PMID 39138191, 2024). "It was not proven until 2020 that caspase-3 cleaving GSDME mediated non-apoptic, non-canonical pyroptosis, and GSDME served as a tumor suppressor, activating pyroptosis and enhancing anti-tumor immunity." (PMID 39000237, 2024). "Also, lobaplatin can activate caspase-3 in CRC cell lines HT-29 and HCT-116, leading to the cleavage of GSDME and subsequent occurrence of pyroptosis-like features, such as plasma membrane swelling and pore formation in CRC cells and inhibiting tumor growth." (PMID 39062587, 2024).
tumor (continued). "The GSDME is not alone in its efforts against anti-tumor immunity; other members of the GSDM family are just as important." (PMID 37705746, 2023). "In addition, GSDME, also known as DFNA5, can induce pyroptosis through caspase-3-mediated cleavage in vitro and suppress tumor growth by activating antitumor immunity." (PMID 37202386, 2023). "Importantly, HMGB1 release and GSDME cleavage were observed upon the challenge of these ORFV recombinants, further confirmed the ability of these ORFV recombinants on triggering tumor cell pyroptosis." (PMID 36641456, 2023). "Moreover, Gasdermin E (GSDME), a crucial pyroptosis-related protein, induces tumor adaptive immunity by promoting macrophage-mediated phagocytosis, thereby adding to the difficulty of immune evasion of cancer cells." (PMID 37071001, 2023). "This conclusion is based on the findings that tumor cells have very little or no expression of GSDME, and that the increased expression of GSDME upon treatment with chemotherapeutic drugs triggers pyroptosis in tumor cells." (PMID 37998332, 2023). "Combined treatment with the v-raf murine sarcoma viral oncogene homolog B1 inhibitor, and MEK inhibitor may achieve the anti-tumor goal by promoting HMGB1 release and GSDME cleavage in DCs113." (PMID 37705746, 2023). "GSDME might modulate immune infiltration through EIF2AK2 and augment the anti-tumor effect of anti-PD-1 therapy." (PMID 38104141, 2023). "As expected, GSDME knockdown reduced the antitumor effect of CC-115, as tumor size reduction was not very significant." (PMID 37283803, 2023). "Furthermore, our data collectively demonstrated that the role of CDC20 depletion in enhancing the infiltration of anti-tumor immune cells, particularly CD8+ T lymphocytes, and this effect is dependent on the presence of GSDME." (PMID 37528490, 2023). "A pivotal study reported that caspase 3/GSDME-mediated pyroptosis is highly dependent on the basal level of GSDME and that tumor cells lacking ‘sufficient’ GSDME develop apoptosis instead of pyroptosis in the context of chemotherapy." (PMID 36641456, 2023). "Gasdermin E (GSDME), a crucial component of the gasdermin (GSDM) family proteins, has the ability to convert caspase-3-mediated apoptosis to pyroptosis of cancer cells and activate anti-tumor immunity." (PMID 38104141, 2023). "Furthermore, cleavage of GSDME and release of HMGB1 activate DCs, eventually leading to T cell proliferation, thereby exerting anti-tumor effects." (PMID 37705746, 2023). "Compared with the vehicle, 5-Aza-CdR monotherapy promoted GSDME expression but did not affect tumour growth." (PMID 35517821, 2022). "In our xenograft GC mice, combining SIM with GSDME overexpression demonstrated a tumour-specific targeting, and none of the main organs examined displayed observable damage." (PMID 35517821, 2022). "Notably, the cleavage and activation of gasdermin-E mediated by granzyme B released by natural killer (NK) cells and CD8+ T lymphocytes can induce pyroptosis of tumor cells." (PMID 35281845, 2022). "In summary, the data in this study show that GSDME, by virtue of its upregulation in PDAC tumour cells, mediates the transcription factor YBX1 to enter the nucleus where it promotes mucin expression, which in turn enables tumour cells to escape pancreatic enzymatic digestion." (PMID 35292781, 2022). "Our cell viability assays showed that knockout of GSDME abrogated the resistance of PDAC tumour cells to pancreatic digestive enzymes, which suggests that GSDME is required for cell survival rather than the known pore-formation role that causes cell death." (PMID 35292781, 2022). "Due to promoter or mRNA methylation, GSDMA, GSDMC, and GSDME are expressed at low levels or are not in tumours." (PMID 35289335, 2022).
tumor (continued). "A recent study identified that small molecule inhibitors BI 2536 and (S)-(+)-camptothecin via organoid-based drug screen were able to induce GSDME-mediated pyroptosis concurrent with caspase-3-dependent apoptosis, which suppressed CRC tumor growth and enhanced the efficacy of immunotherapy." (PMID 36505474, 2022). "In addition, GSDME-mediated pyroptosis promoted the development of CAC by releasing high-mobility group box protein 1 (HMGB1), which boosted tumor cell proliferation through the ERK1/2 pathway." (PMID 36505474, 2022). "For instance, human GSDME, broadly considered as tumor suppressor gene, reduces xenograft tumor growth in immunocompetent but not in immunodeficient mice." (PMID 35281099, 2022). "Tumor cells, but not normal cells, tend to downregulate GSDME, which partly explains the off-target toxicity of some cancer therapies." (PMID 35517498, 2022). "In vivo experiments showed that upregulating OTUD4 or silencing GSDME did not significantly affect xenograft tumor growth without ionizing radiation." (PMID 36411454, 2022). "The study further suggested that GSDME silencing can reverse DDP-induced NSCLC growth inhibition rather than tumor regression in vivo." (PMID 36523974, 2022). "CASP8, CASP6, GSDME, NOD1, and GPX4 were significantly upregulated in tumor tissues compared to the normal tissues, whereas IL6, IL1B, NLRP3, and NLRC4 were downregulated, suggesting that pyroptosis-related genes play important roles in tumor progression and prognosis." (PMID 35559014, 2022). "Meanwhile, transfection of NLS-YBX1 into GSDME−/− AsPC-1 and PANC-1 cells rescued the resistance to trypsin and chymotrypsin; however, the transfection of NLS-GSDME into YBX1−/− tumour cells did not have such an effect." (PMID 35292781, 2022). "On the one hand, chemotherapeutic drugs could promote the cleavage of gasdermin E (GSDME) by activating Caspase-3, to transform apoptosis into pyroptosis and promote tumor cell death." (PMID 35414025, 2022). "Thus, our nanotoxin approach aims to overcome tumor resistance and increase cure rates in HNSCC, by switching cell death induction from apoptosis to caspase-3/GSDME-dependent pyroptosis, as pursued in other cancer types." (PMID 35120582, 2022). "Importantly, patients with high GSDME expression exhibited elevated LDH levels and rapid tumor regression after radiotherapy, as verified by nasopharyngoscopy or MRI." (PMID 36411454, 2022). "First, because GSDME is upregulated along with the EMT process and remains functionally intact, pharmaceutical strategies activating GSDME-dependent pyroptosis present a specific opportunity for targeting human neoplasms with mesenchymal characteristics." (PMID 34901025, 2021). "Furthermore, BRAFi + MEKi induces GSDME-mediated PCD, following by intra-tumoral immune reactions involving the release of inflammatory factors, intra-tumor dendritic cell (DC) activation, and T cell abundance extension." (PMID 34335940, 2021). "Besides, we showed that triclabendazole significantly reduced the tumor volume by promoting the cleavage of caspase-3, PARP, and GSDME in the xenograft model." (PMID 34305590, 2021). "For example, gasdermin B (GSMDB) and gasdermin E (GSDME) are cleaved into their membrane pore-forming fragments by the enzymes granzyme A and B, respectively, when granzymes are delivered directly into the tumor cell during the attack by cytotoxic T cells." (PMID 33868312, 2021). "Since GSDMA and GSDME exert critical tumour‐suppressive effects on tumorigenesis, upregulation of GSDMA/GSDME and induction of GSDMA/GSDME‐related pyroptosis might be a promising therapeutic target for the treatment of cancer." (PMID 34590363, 2021). "Uncleavable GSDME (D270A) or pore-forming defective F2A nonfunctional mutants also fail to inhibit tumor growth, indicating tumor suppression by GSDME is dependent on its activity to execute pyroptosis." (PMID 33941231, 2021).
tumor (continued). "It was found that siRNAs targeting AA388235 activated the response of human tumor cells to exogenous nucleic acids then induced pyroptosis and apoptosis in the presence of GSDME, but only apoptosis in the absence of GSDME." (PMID 34195074, 2021). "The authors provided further evidence that GSDME-mediated tumour inhibition was reduced significantly in mice lacking either CD8+ T or NK cells, indicating that killer lymphocytes mediate tumour suppression of GSDME." (PMID 32404864, 2020). "Herein, we firstly revealed that CAP, as one physical factor but not the conventional chemical or biological ones, induced GSDME-mediated pryoptosis in tumor cells and the basal level of GSDME was positively correlated to the sensitivity to CAP treatment." (PMID 32341339, 2020). "Together, our results indicated that the basal expression level of GSDME in tumor cells was closely related to CAP sensitivity and GSDME might be a potential biomarker of prognosis in the forthcoming cancer CAP treatment." (PMID 32341339, 2020). "As is well known, most of GSDME is expressed in various normal tissues, and is absent in most tumor cells." (PMID 33133646, 2020). "Consistent with the in vitro result of tunnel analysis, GSDME knockout did not affect the apoptotic character of cell death in tumour tissues treated with lobaplatin." (PMID 30804337, 2019). "During the treatment of malignant tumors, appropriate chemotherapeutic drugs can be selected according to the expression levels of DFNA5/GSDME, which can be upregulated in tumor cells, thereby increasing the sensitivity to chemotherapeutic drugs and reducing drug resistance." (PMID 31501419, 2019). "Importantly, the absence of GSDME in tumors results in reduced NK cells presence in the tumor microenvironment." (PMID 41144149, 2025). "In addition, we identified tumor-promoting functions of GSDME in GB that are independent of pyroptosis." (PMID 40544161, 2025). "To determine whether the effect is mediated by IL-12, we used flow cytometry and observed that the expression of GSDME in tumor cells did not affect the total number of CD4+ T cells in vitro." (PMID 38169676, 2024). "Importantly, recent studies demonstrated that an overexpression of GSDME in tumors without the addition of an exogenous activating signal was sufficient to induce pyroptosis and inhibit tumor cell growth." (PMID 38391959, 2024). "This lack of success may stem from GSDME being under-expressed in many tumor cells while over-expressed in normal cells, resulting in reduced effectiveness and potential harm to healthy tissues." (PMID 39742284, 2024). "On the other hand, GSDME activation might transform non-inflammatory apoptosis into inflammatory pyroptosis, activating anti-tumor immunity." (PMID 37771587, 2023). "Notably, numerous studies have demonstrated that GSDME exhibits low or absent expression levels in most tumor cells because of promoter hypermethylation." (PMID 38016064, 2023). "In addition, the negative correlation between tumor mutation burden (TMB) and PANRG-score was revealed by spearman’s correlation analysis and the negative correlations between TMB and DDX3X, CASP7, GSDME expression levels were also uncovered (all P < 0.005)." (PMID 37666920, 2023). "Interestingly, the provided findings offer a hint into the non-pore forming function of GSDME, unravelling the ability of GSDME to act as a transcriptional cofactor of ZEB1 to fuel the ET-1-triggered metastatic progression and tumor immune microenvironment reprogramming." (PMID 37507791, 2023). "As the research deepens, we have discovered that the lack of GSDME expression may be related to tumor chemotherapy resistance." (PMID 36867605, 2023). "The elevated methylation of GSDME determines that tumor cells undergo pyroptosis rather than apoptosis, which indicates that combining methylase inhibitors and antineoplastic drugs may kill tumor cells more effectively." (PMID 38104141, 2023).
tumor (continued). "In addition, caspase-8 in tumor cells can be activated by TNF-α to cleave GSDMC, while in murine macrophage, activation of caspase-8 in the context of TAK1 inhibition results in cleavage of both GSDMD and GSDME." (PMID 36823153, 2023). "Another study by Zhang and colleagues reported that CD8 + T cells and NK cells could evoke pyroptosis of tumor cells independent of caspases through the GSDME-GZMB axis, which is induced by interferon-γ (IFNγ)." (PMID 37730669, 2023). "Furthermore, non-cleavable or pore-defective GSDME loses its tumor-suppressive function, underscoring the importance of pyroptosis in activating antitumor immunity." (PMID 38066523, 2023). "Current research on GSDME mainly focused on cancer treatment and confirmed its tumor suppressive effects, while un-cleavable or pore-defect GSDME proteins could not repress tumor due to inactivating pyroptosis." (PMID 35782390, 2022). "Insulin-like growth factor 2, insulin and glucagon are not involved in GSDME-SG-mediated tumour cell death in vitro; therefore we speculated that exocrine enzymes are involved in GSDME-deficient tumour cell death." (PMID 35292781, 2022). "However, studies have found that, compared with normal cells, GSDME is not expressed in most tumor cells." (PMID 35647057, 2022). "Likewise, tetraarsenic hexoxide (As4O6) could inhibit the phosphorylation of mitochondrial STAT3 and activate mitochondrial ROS-mediated GSDME pathway, to induce pyroptotic cell death in TNBC cells, and finally inhibit tumor growth and metastasis of TNBC." (PMID 35414025, 2022). "More attractively, the siRNA targeting mouse-specific lncRNA AA388235 could facilitate tumor cells pyroptosis through the caspase-3/GSDME signaling pathway, while in the absence of GSDME, tumor cells would undergo apoptosis (Chen Y.-R." (PMID 35419365, 2022). "Gasdermin E could facilitate the phagocytosis of tumor cells by macrophages and increase the number and efficiency of CD8+ T cells and natural killer (NK) cells, thereby inducing the pyroptosis of tumor cells and forming a positive feedback loop." (PMID 35242763, 2022). "Furthermore, we proposed a mechanism by which tetraarsenic hexoxide induced pyroptotic cell death via mitochondrial ROS-mediated caspase-3/GSDME pathway by inhibiting phosphorylation of mitochondrial STAT3, thereby suppressing tumor growth and metastatic potential of aggressive TNBC cells." (PMID 33558527, 2021). "The mechanism studies showed that these siRNAs could activate the response of human tumor cells to exogenous nucleic acids, induce pyroptosis and apoptosis in the presence of GSDME, but induce apoptosis in the absence of GSDME." (PMID 34195074, 2021). "Moreover, other studies showed that GSDMD/GSDME mRNA methylation induces decreased GSDMD/GSDME expression levels in tumor cells when compared with normal cells, making it difficult to activate pyroptosis in tumor cells." (PMID 33840390, 2021). "Though, small molecule drugs such as cannabidiol and miltirone may induce HCC cell death through GSDME-mediated pyroptosis, non-cleavable or pore-defective GSDME was also proved to be not tumor suppressing." (PMID 34925465, 2021). "It is reasonable to speculate that blocking the executors of pyroptosis (such as GSDME), consuming the DAMPs released from pyroptotic cells, or improving CAR-T design to cause tumor cell apoptosis but not pyroptosis may be possible strategies to reduce CARTOX." (PMID 33504767, 2021). "Unlike GSDMD, GSDME has been reported as a tumor suppressor in several studies." (PMID 31616642, 2019). "Together, these findings unveil GSDME as a key transcriptional regulator of aggressive behaviors and worse prognosis in HG-SOC patients, in an ET-1-driven alliance with ZEB1, which could be targeted by ET-1R antagonist to reduce the metastatic burden of this tumor." (PMID 41545335, 2026).